ANKRD44 (ankyrin repeat domain 44)
Description:
Putative regulatory subunit of protein phosphatase 6 (PP6) that may be involved in the recognition of phosphoprotein substrates.
Synonyms: PP6-ARS-B; ARSB
Tractability: PROTAC: ubiquitination databases record sites on it; its protein half-life has been measured.
Target class: Protein phosphatase regulatory subunit; Phosphatase; Enzyme; Protein Phosphatase
Gene: Protein-coding gene on chromosome 2 (196,967,017 to 197,311,173, reverse strand). Ensembl gene ENSG00000065413.
Subcellular location (Human Protein Atlas): Mitochondria; Nuclear speckles
Gene Ontology:
Molecular function: protein binding
Genetic constraint (gnomAD): Loss-of-function variants: 28 observed, 105.03 expected, observed/expected ratio (o/e) 0.27, 90% interval 0.2 to 0.37. The upper end of that interval is the gene's LOEUF score, 0.37, which puts it in group 1 of 6, group 1 being the genes least tolerant of losing a copy. Missense variants: 972 observed, 1,245.9 expected, observed/expected ratio (o/e) 0.78, 90% interval 0.74 to 0.82. Synonymous variants: 419 observed, 469.46 expected, observed/expected ratio (o/e) 0.89, 90% interval 0.82 to 0.97.
Homologues: Orthologues: chimpanzee ANKRD44 (99% identical), macaque ANKRD44 (98% identical), pig ANKRD44 (96% identical), mouse Ankrd44 (96% identical), rabbit ANKRD44 (96% identical), rat Ankrd44 (95% identical), dog ANKRD44 (94% identical), guinea pig ANKRD44 (93% identical), zebrafish ankrd44 (70% identical). Paralogues in human: ANKRD28 (68% identical), ANKRD52 (62% identical), ANKRD55 (16% identical).
Diseases named in the same sentence as ANKRD44 in open-access papers:
ANKRD44 is named in the same sentence as 8 diseases in open-access papers, as found by Europe PMC text mining. Sharing a sentence is not in itself a finding about the gene and the disease. The quoted sentences say what the papers report.
breast carcinoma (2 papers, 2019 to 2026). "The ANKRD44 gene was silenced in Her2-like breast cancer cell line (BT474), obtaining a partially Trastuzumab-resistant breast cancer cell line that constitutively activates the NF-kb protein via the TAK1/AKT pathway." (PMID 31297336, 2019). "ANKRD44 gene silencing constitutively activates the NF-kb protein via the TAK/AKT pathway, which leads to trastuzumab resistance via cell proliferation and glycolysis in breast cancer cells." (PMID 41601635, 2026).
Hypercholesterolemia (1 paper, 2023). An increased concentration of cholesterol in the blood. "In a study looking for genetic drivers of stroke in cerebral arteries, Ankrd44 was downregulated in veins from rabbits with hypercholesterolemia alone and with combined hypercholesterolemia and hypertension." (PMID 37944753, 2023).
schizophrenia (1 paper, 2023). A major psychotic disorder characterized by abnormalities in the perception or expression of reality. "The T allele of rs979020 is associated with increased expression of ANKRD44, decreased risk of schizophrenia, and reduced volume of the hippocampal presubiculum." (PMID 36798360, 2023).
cancer (1 paper, 2023). A tumor composed of atypical neoplastic, often pleomorphic cells that invade other tissues. "ANKRD44 and ATP8B2 were rarely reported in any cancer research." (PMID 36973645, 2023).
ANKRD44 also shares sentences with these, for which no sentence is quoted: Hypertension (1 paper); Stroke (1); systemic lupus erythematosus (1); tumor (1).